CXCL16 (C-X-C motif chemokine ligand 16)
Diseases named in the same sentence as CXCL16 in open-access papers (continued):
Sharing a sentence is not in itself a finding about the gene and the disease.
tumor (continued). "Our data suggest possible direct effects of CXCL16/CXCR6 on cancer cell growth and thereby on tumor development." (PMID 19690611, 2009). "Taken together, our data suggest that CXCL16 and CXCR6 may mark cancers arising in an inflammatory milieu and mediate pro-tumorigenic effects of inflammation through direct effects on cancer cell growth and by inducing the migration and proliferation of tumor-associated leukocytes." (PMID 19690611, 2009). "We have expanded our previous analysis of HAI-2/SPINT2 promoter methylation in RCC (38%) to incorporate all tumours analysed for KTN19 and CXCL16 promoter methylation." (PMID 18195710, 2008). "In addition to this highly inflammatory phenotype, expression of other pro-inflammatory genes, such as IL1B, CXCL16, VEGFA and HBEGF, which can facilitate tumor progression and survival, were also observed." (PMID 41056512, 2025). "Additionally, azvudine regulated the interactions from other tumor immune cells to CD4+ T and CD8+ T cells through ligand‒receptor pairs such as COL1A2‒(ITGA1 + ITGB1), CCL4‒CCR5, CCL6‒CCR2, and CXCL16‒CXCR6." (PMID 39819859, 2025). "When co-culturing CAR T cells with TB32043mb6s2 cells in vitro, a significant secretion of CXCL2, CXCL16 and CCL17 was observed, which are potentially tumour-promoting factors that could hinder therapeutic efficacy in vivo." (PMID 40361460, 2025). "CAFs contribute to ECM production by secreting CXCL16 and enhancing MMP expression, which increases tumor stiffness and alters ECM structure.The binding of PF4/CXCL4 and PPBP/CXCL7 to CXCL12, mediated by G protein-coupled receptors, promotes EMT and the expression of chemokines and cytokines." (PMID 40038745, 2025). "Functionally, we discovered that CXCL16+ glyCAF act as a barrier between CD8+ T cells and malignant cells, thereby preventing T-cell contact with cancer cells and infiltration into the inner tumor parenchyma." (PMID 38509063, 2024). "In RCC, the expression of CXCL16 and its cognate receptor CXCR6 also associates with better survival outcomes in patients; however, neither has been linked with VHL loss or tumor-infiltrating lymphocyte (TIL) infiltration." (PMID 38618956, 2024). "Importantly, CXCL16+ macrophages and dendritic cells recruited CXCR6+ T and NK cells, which exhibited enhanced cytotoxicity, thereby amplifying anti-tumor immunity." (PMID 39588301, 2024). "In addition to CSF1 and IL-4-mediated TAM reprogramming, the chemokine CXCL16 released from tumor cells has also been shown to bind to CXCR6 on microglia cells and drive them toward a pro-tumor phenotype." (PMID 38254796, 2024). "Tumor-supporting activity is related to facilitating tumor invasion, proliferation and migration (mediated by CD204, CD206, CXCL16, stabilin-1, and RAGE), M2-like TAM polarization (by CD36, LOX-1, CXCL16, CD163, and RAGE), and tumor angiogenesis (by CD68, Dectin-1, and RAGE)." (PMID 39516356, 2024). "Furthermore, MEPs increased the tumor cell killing activity of CD8 + T cells and NK cells, an effect that was dependent on MEP-secreted CCL5 and CXCL16." (PMID 36646904, 2023). "Moreover, CXCL-16 inhibited the residency of CD8+ resident memory T cells (TRMs) and therefore facilitated tumor metastasis." (PMID 37173968, 2023). "If these receptors on tumor cells are similarly inhibited by RANKL, then inhibition of RANKL by denosumab would increase their expression and enhance pro-tumoral signaling by the osteoid cell-derived chemokines CCL2, CCL5, CXCL16, and CX3CL1." (PMID 37025604, 2023). "Obtained results suggest the usefulness of CXCL5 and CXCL16 in the determination of distant metastases and differentiation between TNM (Tumor-Node-Metastasis) stages, as well as the usefulness of CXCL14 and CRP combination in CRC detection (primary or recurrence)." (PMID 37848726, 2023).
tumor (continued). "Three of them (CXCL10, CXCL6 and CXCL16) belong to the chemokine (C‐X‐C motif) ligand (CXCL) family, which are known to play key roles in inflammatory diseases, neoplastic transformation and tumour growth regulation." (PMID 36608258, 2023). "Knowing how the CXCL16/CXCR6 axis is expressed by myeloid cells and T cells in tumors, the next step was to understand how this axis influences the composition of immune cell populations in the tumor microenvironment." (PMID 38299146, 2023). "Secondly, RT can regulate the TME, effectively promote the infiltration of CD8+ T lymphocytes by increasing the levels of chemokines CXCL10 and CXCL16 in TME, and reducing immune-related suppressor cells in the tumor stroma, shifting the TME transition from cold tumor to the hot tumor." (PMID 36875059, 2023). "Interestingly, tumor-bearing MMTV-PyMT Osmr-KO mice compared with control mice showed reduced serum VEGF and CXCL16 levels and exhibited a trend toward a decrease in CXCL1, all factors being involved in myeloid cell recruitment." (PMID 35192545, 2022). "On the one hand, CXCL10 secreted by TA-MSCs bind to its cognate receptors CXCR3 presented in cancer cells, and simultaneously, CXCL16 derived from cancer cell bind to CXCR6 on TA-MSCs surface, eventually potentiating the recruitment of TA-MSCs into tumor areas." (PMID 36324128, 2022). "We detected higher percentages of CXCL16+ DCs in the MWA plus TIGIT group compared with the MWA group, indicating that the combination of TIGIT blockade and MWA induced immunoreactivity and enhanced tumor control." (PMID 35320940, 2022). "Many effector cells then travel through the bloodstream to the tumor site by involving various chemokines (e.g., C-C motif chemokine ligand 2 (CCL2), C-X-C motif chemokine ligand 2 (CXCL2), and C-X-C motif chemokine ligand 16 (CXCL16))." (PMID 35456701, 2022). "Whereas co-culture of DCs with ORFV NA1/11-infected LLC cells did not alter significantly the levels of CXCL16 in the supernatants of cultured cells (data not shown), implicating that increased CXCL16 was secreted by tumor cells." (PMID 35959371, 2022). "Tumor-supporting activity mediated by macrophage SRs includes regulation of tumor invasion, proliferation and migration (for CD204, CD206, CXCL16, Stabilin-1, and RAGE), as well as M2-like TAM polarization (for CD36, LOX-1, CXCL16, CD 163, and RAGE) and tumor angiogenesis (for CD68, Dectin-1, RAGE)." (PMID 36686729, 2022). "Accordingly, we tested the hypothesis that ORFV NA1/11 infected tumor cells were more effective to recruit CD8 T cells, which was mediated by CXCL16." (PMID 35959371, 2022). "CXCL16-positive DCs enhance iNKT cell-dependent IFN-γ production and inhibit tumor growth." (PMID 35320940, 2022). "In addition, CXCL16 can recruit CD4+ T cells and NKT cells to kill these senescent aging tumor cells." (PMID 35915657, 2022). "Furthermore, CXCL16 is highly produced by tumor cells and CXCR6− TEff/EMs are the major subset preferentially egressing the tumor to form distant TRMs." (PMID 33979626, 2021). "We counted the metastases on the surface of the lung and found that the number of tumor nodules was not statistically different between control IgG and anti-CXCL16 treated mice." (PMID 33979626, 2021). "We performed qPCR analysis for Cxcl16 mRNA with tumor, tumor-adjacent mucosa, distant mucosa, and non-draining lymph node tissues isolated from 4T1 tumor-bearing mice, while the mammary gland mucosa of tumor-naive mice served as a control." (PMID 33979626, 2021).
tumor (continued). "Distinct chemokines, in particular CXCL12, CXCL16, and CX3CL, are essential for tumor preservation with their autocrine or paracrine signaling promoting anti-apoptotic effects or proliferation of many tumor types including GBMs." (PMID 32346064, 2020). "A cleavable antibody specifically targeting mesothelin+ tumor cells and containing the chemoattractant CXCL16, which binds CXCR6, improved NK cell infiltration after adoptive transfer, which reduced tumor burden and prolonged survival in orthotopic or metastatic PDA murine models." (PMID 33584701, 2020). "Moreover, radiation maintains tumor specific molecular immunity and enhances the secretion of tumor cytokines (CXCL9, CXCL10 and CXCL16) to promote tumor immune recognition and T cell infiltration and inducing immunogenic cell death (ICD)." (PMID 29958545, 2018). "Moreover, radiation-induced tumor lysis led to a decrease in tumor CXCL10 secretion, while the levels of CXCL16 secreted by the APCs into the circulation increased, thereby attracting T cells to the TME and increasing the number of TILs." (PMID 30519541, 2018). "To investigate whether CXCL16/CXCR6 also modulates cell migration, invasion and proliferation in human GBM, we isolated tumor cells from patient's derived biopsies (GBM 13, 19, 40, 45) and analyzed their expression of CXCL16 and CXCR6 by RT-qPCR." (PMID 30542347, 2018). "Moreover, blocking of CXCR4, the chemokine receptor for CXCL12, and neutralization of CXCL16, the ligand for CXCR6 in patient-specific cancer cells significantly prevented the migration of cancer cells to the tumor microenvironment (TME)." (PMID 28649646, 2017). "Within these tumors, the CXCL16/CXCR6 axis plays a multifaceted role by promoting proliferation and migration of tumor cells and attraction and modulation of immune cells supporting immune-mediated tumor control." (PMID 28698473, 2017). "Thus, CXCL9, CXCL10, CXCL16, CCL5, and CX3CL1 can be used to efficiently mobilize CTLs from regional lymph nodes to tumor tissues with an objective to enhance CTL-mediated tumor destruction." (PMID 24966464, 2014). "CXCL16 and CXCR6 levels increase as tumor malignancy increases in some literatures." (PMID 23941552, 2013). "CXCL16 expression has been described on macrophages, dendritic cells, podocytes, epithelial cells, tumor cells; however, the expression of CXCL16 on B cells is not well established yet." (PMID 22454615, 2012). "Another group, surveying 63 cytokines, found that CXCL16 levels went down after 30 Gy irradiation of skin (not tumor) in a murine model." (PMID 23233905, 2012). "Thus, cytokines reported as contributors to tumor progression, such as RANTES, MIP-1γ/CCL9, VEGF, p-Selectin, G-CSF, and CXCL-16, are upregulated in VMR-CM, whereas only the metastasis inhibitor MIP-2 is increased in CSML0-CM." (PMID 20442771, 2010). "Our study is the first to describe expression of the chemokine CXCL16 and its receptor CXCR6 on both cancer cells and adjacent T cells in human cancer and demonstrate correlations between expression of CXCL16 and CXCR6 and tumor progression." (PMID 19690611, 2009). "In contrast, for tumours with CXCL16 methylation (but not for unmethylated tumours), methylation was also detected in the adjacent normal tissue." (PMID 18195710, 2008). "CXCL16 plays roles in the inflammatory response, cell proliferation and migration, and angiogenesis by promoting STAT3 phosphorylation and activating the STAT3/NF-κB pathway in islet-related inflammatory reactions (such as Type I diabetes) and tumour-related inflammatory reactions." (PMID 40165931, 2025). "Similarly, infection by F. nucleatum leads to an increased abundance of tumor-derived EVs, which carry specific miRNAs (miR-1246, 92b-3p, 27a-3p) and protein cargos (CXCL16, RhoA, and IL-8) to non-infected cells, enhancing their migratory capabilities." (PMID 39921821, 2025).
tumor (continued). "In vivo, SBI-457 reduced tumor burden and blocked sorafenib-driven nuclear accumulation of β-catenin, while in vitro screening revealed enhanced responses in HCC cell lines characterized by high soluble CXCL16 secretion and expression of a higher-molecular-weight CXCR6 isoform." (PMID 41375019, 2025). "Radiotherapy also induces the expression and release of chemokines such as CXCL9, CXCL10, and CXCL16 in tumor cells, promoting the migration of effector T lymphocytes to tumor sites, modulating the immune status of the TME, and activating the body’s anti-tumor immune response." (PMID 38809459, 2024). "We further found that CXCL16 was highly expressed in Macro_APOE/CTSZ and CXCR6 was expressed in Treg, which might indicate that Macro_APOE/CTSZ utilized CXCL16 signals to recruit Treg cells to the tumor site, further exacerbating the immunosuppressive TME." (PMID 36587392, 2023). "Moreover, upregulated CXCL16-related DEGs from the human study tumors were significantly decreased in the tumors from the CXCL16-depleted cells, indicating that CXCL16 may actively modulate the protumorigenic conditioning of the PTC tumor microenvironments." (PMID 31527616, 2019). "However, the metastatic effect of tumor cell-derived CXCL16 on colorectal liver metastasis has not been clarified." (PMID 25495942, 2014). "Furthermore, RT modifies the tumor microenvironment by enhancing the release of CXCL16 from tumor cells and upregulating VCAM-1 on the tumor vasculature to favor the recruitment and trafficking of tumor specific cytotoxic T cells to tumor tissue." (PMID 22666458, 2012). "Together our data suggest that CXCL16 and CXCR6 may contribute to tumor progression directly through effects on cancer cell growth, and indirectly, by enhancing leukocyte recruitment and proliferation and the interactions between leukocytes and pre-malignant/malignant cells." (PMID 19690611, 2009). "However, the tumor continues to progress (Relative Tumor Burden >1.5 fold increase, Day 28 vs Day 14), potentially due to a significant increase of Cluster 0 cells after CXCL16 neutralization, suggesting the dynamic nature of the TIME in response to immune modulator CXCL16." (PMID 37055410, 2023). "While a genome-wide association study identified a positive correlation between LCL CXCL16 expression and EBV copy number, it is not known if CXCR6 is required for the effective trafficking of VST to EBV PTLD tumor sites." (PMID 39011042, 2024). "To date, there has not been a review summarizing current knowledge on CXCL16 and its receptor CXC motif chemokine receptor 6 (CXCR6) in a tumor." (PMID 33800554, 2021). "A difference was found between male mice with and without primary tumor differed in IL-10 and IL-16 levels, which were higher in those with tumor, and in CXCL5, CXCL11, CXCL13, CXCL16, and CCL24 levels, which were higher in those without tumor." (PMID 32545680, 2020). "In spite of the fact that CXCL16 can attract CD8+ T cells and NKT cells, which are cells with cytolytic powers, this does not seem to hinder tumor progression." (PMID 31752131, 2019). "We found that the transmembrane chemokine CXCL16 was also frequently methylated in RCC cell lines and in primary tumours but not in normal kidney from non-cancer controls." (PMID 18195710, 2008).
cancer (142 papers, 2008 to 2026). A tumor composed of atypical neoplastic, often pleomorphic cells that invade other tissues. "Consistent with this phenotype, PT-associated macrophages expressed inflammatory cytokines (TNF, IL6) and pro-tumorigenic factors (CCL2, CCL3, CCL4, CXCL16) linked to cancer progression and invasiveness." (PMID 41346635, 2025). "The researchers found that cancer-associated fibroblasts in MPE produce a protein called CXCL16, which attracts TNFR2+ Treg cells." (PMID 41310104, 2025). "Here we demonstrate that the C–X–C motif chemokine ligand 16 (CXCL16)/C–X–C chemokine receptor type 6 (CXCR6) axis plays a critical role in recruiting TNFR2+ Treg cells to MPE, with cancer-associated fibroblasts serving as the primary source of CXCL16." (PMID 41310104, 2025). "Sildenafil and vardenafil treatment of breast cancer associated fibroblasts reduced CXCL16 chemokine expression, thus inhibiting cancer progression and increasing the efficiency of both chemotherapy and radiotherapy." (PMID 39355618, 2024). "ADAM10 has been associated with various cancers owing to its capacity to cleave exo-domain of CXCL16 that correlates with poor survival of OvCa patients." (PMID 30792527, 2019). "The CXCR6/CXCL16 axis has a rather bad press as its increased activity was shown to be associated with invasion of some cancers and development of cardiometabolic disorders." (PMID 31205472, 2019). "Treatment with a CXCR4 antagonist and/or CXCL16 neutralizing antibody, alone or in combination, significantly inhibited migration of cancer cells to brain metastatic cancer-associated fibroblast aggregates." (PMID 28649646, 2017). "The combination of high stromal and high cancer cell CXCL16 was also significantly associated with an improved DSS (P = 0.016)." (PMID 26021984, 2015). "Utilizing TMA methodology on an unselected NSCLC cohort from two hospitals, we show that high stromal CXCL16 expression as well as combined high stromal/cancer cell expression of CXCL16 is associated with a favorable DSS." (PMID 26021984, 2015). "For this reason, CXCL16 is considered an inflammation marker associated with cancer." (PMID 33800554, 2021). "Similarly, we found the CXCL16 → CXCR6 LR pair to be positively associated with the immune response for all 18 cancer types." (PMID 34430923, 2021). "In addition, normal renal tissue showed high endogenous CXCL16 expression, which in turn suggests that reduced CXCL16 expression is linked to cancer development in this organ." (PMID 29285224, 2017). "Cleavage of CXCL16 is an event associated with protease activity of ADAM 10 in many cancers." (PMID 25888629, 2015). "Finally, to investigate a more general association between CXCL16 and inflammation-associated cancers, we studied the expression of this chemokine in specimens from multiple types of human cancers." (PMID 19690611, 2009). "However, in PCa, CXCL16 has been linked to cancer progression and metastasis." (PMID 37025604, 2023). "Interestingly, both normal lung and renal tissue show high endogenous CXCL16 expression, which may suggest that reduced or aberrant CXCL16 expression is linked to cancer development in these organs." (PMID 26021984, 2015). "Decreased cell adhesion upon loss of CXCL16 expression needs yet to be experimentally confirmed, but if it indeed takes place, it might promote detachment of single cancer cells, their migration, and establishment elsewhere as metastatic foci, thus contributing to worse prognosis." (PMID 26021984, 2015). "Finally we demonstrate CXCL16 in multiple human cancers associated with inflammation." (PMID 19690611, 2009). "Its ligand, CXCL16, can be expressed by cancer cells and antigen-presenting cells (APCs), and the interaction of the two has been found to play a key role in recruiting and retaining TRMs in various tissue contexts." (PMID 40862776, 2025).